EGFR (epidermal growth factor receptor)
Diseases named in the same sentence as EGFR in open-access papers (continued):
Sharing a sentence is not in itself a finding about the gene and the disease.
breast carcinoma (continued). "EGFR and ligands such as transforming growth factor-α and amphiregulin are over-expressed in a large subset of primary breast carcinomas." (PMID 18822183, 2008). "This study suggests that S100A7 plays an important role in EGFR-mediated signaling and osteoclast formation in breast cancer." (PMID 18320059, 2008). "In short, we have shown MCF-7 breast cancer cells overexpressing YB-1 have elevated levels of EGFR mRNA and protein." (PMID 19036157, 2008). "Ras signal transduction pathways play an important role in breast cancer progression, as evidenced by the frequent over-expression of the Ras-activating epidermal growth factor receptors EGFR and ErbB2." (PMID 18597688, 2008). "In contrast, we show that activation of EGFR in breast cancer cells significantly alters the motile properties of these cells." (PMID 18435854, 2008). "ErbB2, a member of the epidermal growth factor receptor (EGFR) family, is overexpressed in 20% to 30% of human breast cancer cases and forms oncogenic signalling complexes when dimerised to ErbB3 or other EGFR family members." (PMID 18700973, 2008). "Developing alternative drug targets in the EGFR signalling pathway as means to treat EGFR-dependent invasive and metastatic breast cancer is therefore imperative." (PMID 18435854, 2008). "In contrast, however, there is no affect of TNK2 siRNA on proliferation or apoptosis, which is in agreement with our findings that the main functional effect of EGFR activation in these breast cancer cells is stimulation of motility." (PMID 18435854, 2008). "Basal-like breast cancers (BLBC) frequently overexpress the epidermal growth factor receptor (EGFR) and subsequently have high levels of signaling through the MAP kinase pathway, which is thought to contribute to their aggressive behavior." (PMID 19036157, 2008). "Recently, the importance of the dual suppression of both EGFR and mTOR expressions was shown when the proliferation of breast cancer was synergistically reduced after the inhibition of both EGFR and mTOR expressions." (PMID 18797454, 2008). "Transgenic breast cancer mouse models have confirmed that elevated signaling in the EGFR/HER2-PI3K-Akt pathway either by targeted Akt overexpression or HER2 overexpression in breast epithelial cells induces breast cancer development." (PMID 18518979, 2008). "EGFR expression combined with c-Src overexpression can initiate oncogenic transformation and marked migratory and invasive behavior in human breast cancer cells." (PMID 18320059, 2008). "The role of YB-1 in promoting growth of breast cancer cells stems from its original identification as a DNA binding protein, interacting with the regulatory elements of epidermal growth factor receptor (EGFR), HER-2 and c-MYC." (PMID 19036157, 2008). "EGFR signaling is frequently altered in breast cancer, where EGFR and ErbB2 over-expression are common events." (PMID 18597688, 2008). "EGFR is known to be a positive immunohistochemical marker for basal-like breast cancers and it was shown to accurately identify basal-like tumors from microarray data with potential therapeutic implications." (PMID 19116033, 2008). "We have previously established the importance of phosphorylation of YB-1S102 for its transcriptional activity in breast cancer, and in particular the regulation of EGFR in BLBC." (PMID 19036157, 2008). "In accordance, TNK2 silencing by siRNA led to a significant reduction in cell surface EGFR and to a concomitant decrease in the migratory and invasive capacity of breast cancer cells." (PMID 18435854, 2008). "Four of the established endometrial cancer cell lines (HEC155, SNG-II, SNG-M, and RL-95-2) expressed EGFR at high levels comparable to those seen in breast cancer cells known to express high level of EGFR." (PMID 18334972, 2008). "EGFR is overexpressed in 40% of primary breast cancers and preclinical studies demonstrated the efficacy of the EGFR inhibitor gefitinib in ER-positive EGFR overexpressing tumours." (PMID 18283314, 2008).
breast carcinoma (continued). "Previous studies have shown that nuclear accumulation of EGFR correlates with poor prognosis in breast cancer and oropharyngeal squamous cell carcinomas." (PMID 18177496, 2008). "ERBB2 (HER2) and EGFR (ERBB1, HER1) are growth factor receptors (GFRs), members of the transmembrane receptor tyrosine kinase family, and are overexpressed in 25–30% and 7–20% of breast cancers, respectively." (PMID 19007432, 2008). "We found that the CD44+/CD24- status was associated with low/negative HER2 expression and with elevated expression of CK5/14 and EGFR, as well as with medullary histological type, all known characteristics of the basal-like subtype of breast cancer." (PMID 18559090, 2008). "EGFR gene copy numbers in breast cancer tissues were estimated with 7500 Fast Real-Time PCR using a QuantiTect SYBR Green Kit (Qiagen Inc, Valencia, CA)." (PMID 18950515, 2008). "; however, specific binding of the labeled compounds to the EGFR was demonstrated only in vitro using EGFR positive MDA-MB 468 human breast cancer cells." (PMID 18991714, 2008). "Targeting HER2 has been the main focus in breast cancer 15, 16, 17 although increasingly, inhibition of EGFR in combination with HER2 blockage is seen to be important in breast cancer therapy." (PMID 18682844, 2008). "There is evidence that estrogen receptor positive breast cancers become resistant to hormonal therapy by up-regulating other signaling pathways involved in tumor proliferation such as EGFR, HER2, MAPK and PI3K/Akt." (PMID 18828924, 2008). "Studies of CA-SSR1 repeat length and EGFR expression in breast cancer tissues have shown a constant decline in EGFR expression with increasing repeat length." (PMID 18985035, 2008). "Since Brk signals downstream of the EGFR and HER2 tyrosine kinases, the EGFR/HER2-overexpressing SKBr3 breast cancer cell line and the EGFR-overexpressing BT-20 breast cancer cell line were chosen for these studies." (PMID 17997837, 2007). "A number of different tyrosine kinases, including the epidermal growth factor receptor (EGFR) family of tyrosine kinases, Src, and Jaks, have been described as mediating Stat3 phosphorylation in both primary tumors and breast cancer-derived cell lines." (PMID 17531096, 2007). "In summary, our observations on blocking autocrine WNT activity in human breast cancer cells suggest an important role for WNT-induced EGFR transactivation in the control of ERK1/2 signaling and of proliferation." (PMID 17897439, 2007). "Proposed mechanisms for the origin of ER− breast cancers include that of pressures being exerted on ER+ cells by oestrogen withdrawal, hypoxia, or overexpression of epidermal growth factor receptor or ErbB2 resulting in MAPK hyperactivation." (PMID 17700572, 2007). "Presently anti-EGFR/HER2 therapy for recurrent/metastatic breast cancer is based on immunohistochemistry and fluorescence in situ hybridization of the primary breast cancer tissue." (PMID 17976236, 2007). "It has previously been reported that both YB-1 and EGFR are highly expressed in aggressive forms of breast cancer." (PMID 17875215, 2007). "This oncogenic potential in conjunction with the aberrant expression and/or activation of EGFR, which has been reported in a range of human malignancies including breast cancer, provides a strong rationale for targeting this growth factor receptor." (PMID 17686159, 2007). "The effects of WNT signaling are mediated partly by EGFR transactivation in human breast cancer cells in a metalloprotease- and Src-dependent manner." (PMID 17897439, 2007). "The relationship between CA-SSR1 repeat length and EGFR overexpression has been extensively studied in breast cancers." (PMID 17455987, 2007). "Based on our studies, we propose that HER2, EGFR, c-Src, and Brk all signal downstream to STAT5b to increase proliferation of breast cancer cells." (PMID 17997837, 2007).
breast carcinoma (continued). "The EGFR pathway is a complex signaling network and differences in gene expression levels of its various components can be observed across the breast cancer subtypes." (PMID 17663798, 2007). "Serum EGFR levels in our group of breast cancer patients were significantly lower when compared with those in healthy control individuals." (PMID 17976236, 2007). "The involvement of WNT-induced Src activity on EGFR activation is corroborated by our observation that the knockdown of DVL decreased the level of Tyr 845 phosphorylation in several breast cancer cell lines." (PMID 17897439, 2007). "In breast cancer, the role of EGFR is complex and appears to vary relative to important clinical features including estrogen receptor (ER) status." (PMID 17663798, 2007). "We have, however, shown that knockdown of Brk significantly decreased DNA synthesis in the EGFR-overexpressing and c-Src-overexpressing breast cancer cell lines, SKBr3 and BT-20." (PMID 17997837, 2007). "Previous studies have demonstrated that STAT5a and STAT5b are tyrosine phosphorylated by the EGFR and c-Src kinases, two kinases that are involved in breast cancer." (PMID 17997837, 2007). "It was recently shown that Wnt1 is induced by progesterone receptor (PgR) signaling in T47D breast cancer cells and that it is required for EGFR transactivation by a PgR agonist in an Src- and metalloprotease-dependent manner." (PMID 17897439, 2007). "In the previous Creighton study, ER+ MCF-7 breast cancer cells were made to stably over-express EGFR or constitutively activate erbB-2, Raf, or MEK; which resulted in these cells exhibiting estrogen-independent growth and the down-regulation of ER expression." (PMID 17598908, 2007). "Both STAT5b and STAT3 are activated by several kinases overexpressed in breast cancer, including the EGFR, HER2, and c-Src." (PMID 17997837, 2007). "Here, we examined the effects of a pan-Jak inhibitor (P6), a potent inhibitor of Src (dasatinib, BMS), and an EGFR/Her2neu inhibitor (Gefitinib, ZD) on pStat3 in these breast cancer-derived cell lines." (PMID 17531096, 2007). "A number of clinical trials testing the efficacy of EGFR tyrosine kinase inhibitors (TKIs) in breast cancer treatment are underway." (PMID 17598908, 2007). "Serum levels of EGFR serum levels were significantly higher in normal individuals (median 75.3 ng/ml, range 43.2 to 114.2 ng/ml) than in patients with primary breast cancer (median 59.3 ng/ml, range 21.3 to 94.1 ng/ml; P < 0.001)." (PMID 17976236, 2007). "It has previously been demonstrated that combined targeting of EGFR and erbB2 is more effective than targeting either agent alone in inhibiting growth of erbB2-overexpressing breast cancer cells." (PMID 17686159, 2007). "Such is the case for trastuzumab treatment and soluble Her2/neu ECD in breast cancer, for soluble EGFR during chemotherapy in breast cancer, and for soluble c-kit in response to imatinib treatment in gastrointestinal tumor (GIST) patients." (PMID 17605814, 2007). "STAT5b phosphorylation and activation is mediated by several kinases known to be overexpressed in breast cancer, such as epidermal growth factor receptor, HER2, and c-Src." (PMID 17997837, 2007). "In support of this premise, EGFR and HER2 co-expression has been linked to a more aggressive clinical phenotype and to poor prognosis in breast cancer." (PMID 16622439, 2006). "Overexpression of EGFR is found in 14–91% of breast cancer and this has been correlated with disease progression and poor prognosis." (PMID 16685276, 2006). "A role of nuclear EGFR in prognostic prediction is further suggested in patients with breast carcinomas and oropharyngeal squamous cell carcinomas." (PMID 16434982, 2006). "Consistently, a positive correlation has been found between nuclear EGFR and cyclin D1/iNOS in a cohort of breast carcinomas." (PMID 16434982, 2006).
breast carcinoma (continued). "The finding of the c-kit expression of breast cancer is quite a contrast to the finding of EGFR and erbB2 expression of breast cancer, in which the overexpression of EGFR and erbB2 indicated a malignant phenotype of breast cancer." (PMID 16721362, 2006). "Along the same line, in primary breast cancers, a positive correlation was established between high levels of nuclear EGFR and expression of cyclin D1 and Ki-67, two markers of active proliferation." (PMID 17049074, 2006). "The EGFR overexpressing breast cancer cell line MDA-MB-468 forms EGFR homodimers in response to ligand stimulation." (PMID 16306877, 2006). "Although preclinical cell culture and xenograft studies suggest that EGFR targeted therapies hold promise for certain subtypes of breast cancer, clinical trials to date have shown responses in less than 10% of patients." (PMID 16622439, 2006). "We identified the molecular subtypes of breast cancer in 753 out of 885 patients by the combination of four immunohistochemical markers (HER2-positive, luminal ER-positive and basal-like CK5/6, and/or EGFR-positive breast cancer)." (PMID 17088909, 2006). "A recent clinical study has suggested that the adverse prognostic value of HER2 overexpression occurs only with HER2 activation or EGFR co-expression in breast cancer." (PMID 16622439, 2006). "A much stronger negative relation exists between EGF-regulated gene expression and expression association with ER status (rs = - 0.43; P < 0.0001), which concurs with the established inverse relation between ER and EGFR in breast cancer." (PMID 15642172, 2005). "Approximately 70–80% of metaplastic breast carcinomas overexpress the epidermal growth factor receptor (EGFR)." (PMID 16280056, 2005). "In clinical trials, the response to epidermal growth factor receptor (EGFR) inhibitors, such as gefitinib, has varied widely, ranging from rare in breast cancers to 10–30% in metastatic non-small-cell lung carcinoma (NSCLC)." (PMID 15841079, 2005). "In this study, AG1024 and gefitinib were used to cotarget IGF-1R and EGFR activity in several human breast cancer cell lines that express IGF-1R similarly but present different levels of EGFR." (PMID 15987464, 2005). "Twenty-five metaplastic breast carcinomas were immunohistochemically analyzed using a monoclonal antibody (31G7) for EGFR and two antibodies for HER2 (Herceptest and CB11) and scored using the Herceptest scoring system." (PMID 16280056, 2005). "Our group and others have demonstrated that 'basal-like' breast carcinomas and metaplastic breast carcinomas (MBCs) consistently overexpress EGFR but usually lack HER2 overexpression." (PMID 16280056, 2005). "The results presented here show the effects of adding an anti-IGF-1R strategy to gefitinib treatment in human breast cancer cell lines chosen for their similar expression of IGF-1R but their different EGFR levels." (PMID 15987464, 2005). "In a recent study, Bhargava and coworkers demonstrated that 6% (11/175) of all breast carcinomas exhibit EGFR amplification." (PMID 16280056, 2005). "Further studies addressing the efficacy of EGFR inhibitors in this group of breast carcinomas are warranted." (PMID 16280056, 2005). "We have reported that only a minority of erbB2-altered invasive human breast cancers have overexpression of erbB1 (EGFR) and activation of erbB2." (PMID 16168116, 2005). "HER2 overexpression has been identified in 87% and 27% breast carcinomas with EGFR overexpression and gene amplification, respectively." (PMID 16280056, 2005). "Although HER2 gene amplification and protein overexpression have been extensively studied in breast cancer, data on EGFR amplification in breast cancer are limited." (PMID 16280056, 2005). "Low and variable expression of EGFR has also been found in mammary tumors that develop in transgenic mice bearing activated forms of rat c-neu/ErbB2." (PMID 16168116, 2005).
breast carcinoma (continued). "One of the major targets for breast cancer therapy is the epidermal growth factor receptor (EGFR) and related receptors, which signal via different signal transduction pathways including the mitogen-activated protein kinase (MAPK) pathway." (PMID 15280923, 2004). "In this study, expression of EGFR was identified in 20.1% of cases, consistent with previous studies where EGFR expression has been reported in 14–65% of breast cancer." (PMID 15480434, 2004). "In conclusion, our data show that protein-based PLC-γ1 inhibitors are not only potent PLC-γ1 inhibitors but also possess antitumour effects on EGFR/c-erbB-2-positive breast cancer cells due to the inhibition of both proliferation and migration." (PMID 14710234, 2004). "In the present study, we designed an approach to block the EGF-induced cell migration of EGFR/c-erbB-2-positive breast cancer cells by using protein-based PLC-γ1 inhibitors." (PMID 14710234, 2004). "Some clinical studies have shown correlations between ras and myc mutations and resistance to therapy in ovarian cancer, and overexpression of EGFr in breast cancer." (PMID 14760366, 2004). "Our results indicate that high basal activity of ERKs give some breast cancer cells a mechanism to escape the inhibitory effects of EGFR/HER2 tyrosine kinase inhibition." (PMID 15280923, 2004). "In breast cancer, amplification of HER2 is associated with taxol resistance, and in glioblastomas increase in EGFr activity to radiation and BCNU." (PMID 14760366, 2004). "Aberrant EGFR/HER1 signalling, such as high expression of EGFR/HER1, is causally associated with enhanced tumour cell proliferation and shorter survival in patients with solid tumours such as breast cancer." (PMID 14710235, 2004). "As expected from the heterogeneity seen in clinical specimens of breast cancer, there was variability in expression of EGFR, from high expression in MDA-MB-468 and minimal expression in MDA-MB-435 cells." (PMID 15280923, 2004). "In this study 88 primary breast cancers were assayed for EGFR using a novel immunohistochemical assay performed on paraffin-embedded sections." (PMID 7779717, 1995). "Epidermal growth factor receptor (EGFR) has been the subject of much research since it was first described as a prognostic factor in breast cancer." (PMID 7779717, 1995). "The results suggest that ER and EGFR expression are mutually exclusive within an individual breast cancer cell in vivo with separate populations of ER+/EGFR- cells, ER-/EGFR+ cells and ER-/EGFR- cells coexisting." (PMID 8198966, 1994). "This is the first description of a simultaneous dual immunocytochemical assay system for ER and EGFR in clinical breast cancer specimens." (PMID 8198966, 1994). "Recent studies have demonstrated a consistent inverse relationship between oestrogen receptor (ER) and epidermal growth factor receptor (EGFR) levels in female human breast cancer." (PMID 8198966, 1994). "We have examined the prognostic significance of TGF alpha, TGF-beta 1 and EGFR mRNA expression in a series of patients with primary breast cancer with a median follow up period of 60 months." (PMID 8390290, 1993). "The relationship between EGFR status (determined by an immunocytochemical assay) and various prognostic factors was investigated in 164 primary breast cancers." (PMID 1419645, 1992). "The epidermal growth factor receptor (EGFR) is a transmembrane glycoprotein whose expression is important in the regulation of breast cancer cell growth." (PMID 1419645, 1992). "We have examined the expression of receptors for epidermal growth factor (EGFR) by the ZR-75-1 human breast cancer cell line and tamoxifen resistant (ZR-75-9al 8 microM) and oestrogen independent/tamoxifen sensitive (ZR-PR-LT) variants." (PMID 1616857, 1992). "Of 221 patients with breast cancer of known epidermal growth factor receptor (EGFR) and oestrogen receptor (ER) status, 99 had developed recurrences during the period of follow-up (range 3-60 months, median 24 months)." (PMID 1346366, 1992).